IFI16 (interferon gamma inducible protein 16)
Diseases named in the same sentence as IFI16 in open-access papers (continued):
Sharing a sentence is not in itself a finding about the gene and the disease.
cardiovascular disease (2 papers, 2024 to 2025). "IFI16 plays contrasting roles in cardiovascular disease, acting both as a promoter of inflammation and cell death in AAA and as a mediator of cardioprotective effects in response to metformin." (PMID 39158380, 2025). "This dual functionality underscores the importance of context‐specific targeting of IFI16 for therapeutic interventions in cardiovascular diseases." (PMID 39158380, 2025). "The findings suggest a link between IFI16, NLRP3, and HIV progression, emphasizing their potential role in comorbidities such as cardiovascular disease." (PMID 39000248, 2024). "However, our findings further support the involvement of IFI16 and NLRP3 inflammasomes in HIV pathogenesis involving increased release of both IL-1 isotypes that may clearly also be related to the increased occurrence of certain comorbidities such as cardiovascular disorders in PWH." (PMID 39000248, 2024).
infectious disease (2 papers, 2021 to 2025). A disorder directly resulting from the presence and activity of a microbial, viral, or parasitic agent in humans. "Therefore, it is of future interest to evaluate whether pharmacological target of IFI204/IFI16 signaling confers protection in pathogenic infectious diseases." (PMID 41304242, 2025).
metabolic disease (2 papers, 2022 to 2025). A congenital disorder (due to inherited enzyme abnormality) or acquired (due to failure of a metabolically important organ) disorder resulting from an abnormal metabolic process. "Other inflammasomes and molecules related to the activation cascade (e.g., CARD8, AIM2, IFI16, CASP-1, and IL-1β) have also been found to be associated with a variety of infections and metabolic diseases." (PMID 36105941, 2022).
adenocarcinoma (1 paper, 2025). A common cancer characterized by the presence of malignant glandular cells. "The positive correlation between IFI16 expression and immune infiltration was observed exclusively in the adenocarcinoma cohorts (GSE72094 and TCGA-LUAD)." (PMID 41378285, 2025).
gynecological diseases (1 paper, 2026). "We comprehensively summarize the molecular mechanisms of inflammasome activation-particularly NLRP3, AIM2, and IFI16-and their dual roles in inflammatory injury and immune regulation across gynecological diseases." (PMID 42079573, 2026).
heart disease (1 paper, 2024). "Unraveling IFI16’s impact on PANoptosis regulation in heart diseases requires dissecting the molecular interactions underlying its functions." (PMID 38693141, 2024). "Thus, IFI16’s associations with different cell death pathways and its intricate role in PANoptosis regulation suggest a potential nexus for understanding heart disease pathogenesis." (PMID 38693141, 2024). "IFI16’s potential to modulate multiple cell death pathways, interact with inflammation, and influence vascular health underlines its significance in shaping heart disease outcomes." (PMID 38693141, 2024). "It synthesizes evidence of IFI16’s impact on PANoptosis, with the intention of providing novel insights for therapeutic strategies targeting heart diseases." (PMID 38693141, 2024). "The complex biology of heart disease can be better understood by utilizing IFI16’s role in PANoptosis pathways." (PMID 38693141, 2024). "In this review, we navigate the intricate connections between IFI16, inflammation, cell death pathways, and heart diseases." (PMID 38693141, 2024). "Subsequent investigations ought to examine the molecular intricacies of IFI16’s involvement in PANoptosis in heart diseases." (PMID 38693141, 2024). "IFI16’s potential influence on multiple facets of heart disease emphasizes the need to explore its interconnected effects." (PMID 38693141, 2024). "The current study supports a new paradigm in therapeutic approaches by highlighting the significance of IFI16 in cardiac diseases." (PMID 38693141, 2024). "IFI16’s intricate relationship with cell death pathways adds complexity to its role in heart disease." (PMID 38693141, 2024). "In conclusion, the role of PANoptosis regulation, orchestrated by IFI16, may unveil a new layer of complexity in heart diseases." (PMID 38693141, 2024). "IFI16’s unique ability to sense danger, modulate immune responses, and engage in cell death regulation suggests its potential to orchestrate PANoptosis outcomes in heart diseases." (PMID 38693141, 2024). "A comprehensive understanding of IFI16-mediated PANoptosis may pave the way for novel therapeutic strategies targeting the intricate interplay of inflammation and cell death in heart diseases." (PMID 38693141, 2024). "We have the chance to develop novel approaches that might significantly change the therapeutic management of cardiac disease by focusing on IFI16-mediated pathways, providing hope for better patient outcomes and quality of life." (PMID 38693141, 2024).
IFI16 also shares sentences with these, for which no sentence is quoted: diabetes (3 papers); Kaposi's sarcoma (3); lymphoma (3); renal cell carcinoma (3); Behçet disease (2); clear cell renal cell carcinoma (2); esophageal squamous cell carcinoma (2); immune system disease (2); liver cirrhosis (2); abdominal aortic aneurysm (1); abortion (1); acute kidney injury (1); Anxiety (1); bacterial sepsis (1); celiac disease (1); chondrosarcoma (1); chronic hepatitis B (1); chronic kidney disease (1); chronic liver failure (1); Cognitive impairment (1); coinfection (1); colitis (1); depression (1); dermatitis (1); diabetic cardiomyopathy (1); dilated cardiomyopathy (1); epidermodysplasia verruciformis (1); Fanconi Anemia Complementation Group (1); gastric cancer (1); glomerulonephritis (1).
A further 30 diseases each share a sentence with IFI16 in 1 paper.